KCNA1 (potassium voltage-gated channel subfamily A member 1)
Diseases named in the same sentence as KCNA1 in open-access papers (continued):
Sharing a sentence is not in itself a finding about the gene and the disease.
brain disorder (2 papers, 2020). A disease affecting the brain or part of the brain. "Remarkably, given the critical role played by Kv1.1 channels in dampening neuronal excitability, the opportunity to target Kv1.1 appears as a fruitful strategy to treat Kv1.1-associated diseases and brain disorders not linked to KCNA1 abnormalities that are caused by neuronal hyperexcitability." (PMID 32331416, 2020).
neurodevelopmental disorder (2 papers, 2020 to 2024). A behavioral and cognitive disorder with onset during the developmental period that involves impaired or aberrant development of intellectual, motor, or social functions. "By comparing the genotype–phenotype relationships of all patients with KCNA1 variants, it was observed that the phenotypes resulting from variants at the C‐terminus are more likely to be related to neurodevelopmental disorders." (PMID 32705822, 2020). "A novel homozygous KCNA1 variant (p.Val368Leu) in the S5–S6 linker has recently been reported in a patient with neurodevelopmental disorders." (PMID 32705822, 2020). "Next, we systematically reviewed the available clinical phenotypes of individuals with EA1 and observed that individuals with KCNA1 variants at the C‐terminus were more likely to suffer from seizures and neurodevelopmental disorders than those with variants at the N‐terminus." (PMID 32705822, 2020).
genetic disorders (1 paper, 2023). "Advances in genetic testing have broadened the KCNA1 and CACNA1A phenotypes, and detected EA as an unusual presentation of several other genetic disorders." (PMID 37008993, 2023).
KCNA1 also shares sentences with these, for which no sentence is quoted: long QT syndrome (5 papers); diabetes (4); glioma (4); Obesity (4); movement disorder (3); multiple sclerosis (3); SESAME syndrome (3); autism spectrum disorder (2); autoimmune disease (2); deafness (2); Gitelman syndrome (2); Hypokalemia (2); injury (2); Intellectual disability (2); melanoma (2); Morvan syndrome (2); type 2 diabetes (2); Alzheimer disease (1); asthma (1); astrocytoma (1); autosomal dominant disease (1); Bartter syndrome type 3 (1); Bartter syndrome type 4 (1); Benign familial neonatal seizures (1); bipolar disorder (1); Bradycardia (1); brain tumor (1); breast adenocarcinoma (1); breast tumors (1); Brugada syndrome (1).
A further 47 diseases each share a sentence with KCNA1 in 1 paper.